Y_RNA (Y RNA )
Gene: Miscellaneous RNA gene on chromosome 15 (43,247,680 to 43,247,781, forward strand). Ensembl gene ENSG00000202211.
Homologues: Orthologues: chimpanzee Y_RNA (99% identical). Paralogues in human: Y_RNA (90% identical), RNY3 (89% identical), Y_RNA (89% identical), Y_RNA (88% identical), RNY3P1 (87% identical), Y_RNA (87% identical), RNY3P16 (86% identical), Y_RNA (86% identical), RNY3P2 (85% identical), RNY3P9 (85% identical), Y_RNA (85% identical), RNY3P11 (84% identical), and 96 more.